MCL1 (MCL1 apoptosis regulator, BCL2 family member)
Diseases named in the same sentence as MCL1 in open-access papers (continued):
Sharing a sentence is not in itself a finding about the gene and the disease.
leukemia (continued). "Fenretinide was found to promote MCL-1 degradation by a JNK-mediated mechanism and thus has promise in overcoming MCL-1 mediated chemoresistance in ALL and other leukemias." (PMID 20844597, 2010). "We demonstrated that BCL-XL or MCL1 was highly expressed in leukemia cells of patients who did not respond to this treatment." (PMID 41615994, 2026). "It is therefore plausible that CalPegA and S63845 do not synergize due to redundancy in their anti-leukemia mechanisms, but to better understand the limitations in synergy between CalPegA and MCL-1 inhibition, further mechanistic studies are required." (PMID 39684800, 2024). "Next, we assessed whether co-targeting of MCL-1 and BCL-2 would re-sensitize VEN-insensitive leukemia cells and investigated cell death induction by titrating concentrations of VEN, S63845, or their combination." (PMID 38961053, 2024). "Therefore, while venetoclax is highly effective in other types of leukemia cancers, in AML, venetoclax encounters MCL-1-dependent resistance." (PMID 38399263, 2024). "Following its success in other leukemias, though venetoclax only showed modest single-agent activity in AML, strong preclinical data suggesting increased expression of BCL-2 and MCL1 in AML and the possibility of indirectly targeting MCL1 with cytotoxic drugs kept the researchers going." (PMID 37296964, 2023). "Although several Mcl-1 inhibitors have been developed and exhibited promising anti-tumor efficacy in pre-clinical leukemia or solid tumor animal models, there is still a lack of Mcl-1 inhibitors approved for clinical use." (PMID 36658493, 2023). "HMAs might synergistically inhibit MCL1 and BCL-XL, thereby increasing the dependence of leukemia cells on BCL-2." (PMID 37120593, 2023). "Mcl-1 direct inhibitors have not been successfully developed as therapeutics probably due to the unselective inhibition of leukemia and normal cells, and heart toxicity." (PMID 36739272, 2023). "Importantly, the combination treatment resulted in markedly reduced leukemia loads in all compartments, indicating significant synergistic anti-leukemia activity of co-inhibition of BCL-2 and MCL-1 in vivo." (PMID 35031695, 2022). "In SUP-T1 cells, apart from downregulation of the known BRD4 targets like Myc, Bcl-2, Bcl-XL, and Mcl-1, treatment with ARV-825 substantially decreased the expression of key molecules involved in leukemia persistence, such as HES1 (a direct target of Notch1), PI3K/AKT pathway proteins, and CD44." (PMID 35173274, 2022). "To examine whether SIRT3 also inhibited the cytotoxic effect of ABZ-induced MCL1 suppression in other cell lines, we analyzed the cytotoxicity of ABZ on human leukemia MEG-01 cells." (PMID 32486166, 2020). "Indeed, combination of an Mcl-1 inhibitor and ABT-199 did enhance the inhibition of leukemia growth." (PMID 32699295, 2020). "Mcl-1, a member of the Bcl-2 family, is over-expressed in CLL, as well as in other leukemias." (PMID 32517377, 2020). "ALL refractory to glucocorticoids presented with high expression levels of the anti-apoptotic BCL2 family protein MCL1, due to a hyper activation of the PI3K/AKT/mTOR network, and specific MCL1 inhibitors are currently under evaluation for anti-leukemia activity." (PMID 30941349, 2019). "After 6 hours of stimulation with IL-33, we observed significantly increased expression of Bcl-xl, TRAF-1, TRAF-2, and Mcl-1, but not Bcl-2 in leukemia cells." (PMID 30742053, 2019). "Previous studies have shown that CDKIs (e.g., roscovitine) increase the lethality of the BH3-mimetic ABT-737, which inhibits Bcl-2/xL but not Mcl-1, in human leukemia cells." (PMID 28938651, 2017).
leukemia (continued). "In comparison to normal B-cells, Eμ-Tcl1 Tg leukemias exhibited extensive Bcl-2 and Bcl-XL expression, with little or no expression of Mcl-1, Bfl-1/A1 or Bcl-w." (PMID 27843137, 2017). "Reducing the levels of Mcl-1, irrespective of JAK2 mutation, sensitizes leukemia cells to ABT-263, indicating that Bcl-2 family proteins, such as Bcl-xL and Bcl-2, are necessary to maintain viability when Mcl-1 levels are reduced." (PMID 25781882, 2015). "In the present study, our results exhibited that ribavirin inhibited the Mcl-1 synthesis at protein translation not mRNA transcriptional level in Ph+ leukemia cell lines." (PMID 26317515, 2015). "Similarly, down-regulation of Mcl-1 and induction of PARP cleavage were observed in all 5 primary leukemia samples after 6-h exposure to dinaciclib (≥20 nM), but more prominent effects were noted at the 200 nM concentration and with 24-h exposure." (PMID 23949430, 2013). "MCL-1 has been identified as a BCR/ABL-dependent survival factor in CML and acts as an anti-apoptotic factor in various neoplastic cells, including several leukemia-derived cell lines." (PMID 23596478, 2013). "We have also demonstrated that dinaciclib down-regulates the expression of the anti-apoptotic protein Mcl-1 independently of caspases and induces PARP cleavage in leukemia cell lines; however, these effects were most prominent with prolonged exposures (6 and 24 h)." (PMID 23949430, 2013). "It is possible that the simultaneous down-regulation of Mcl-1 and cFLIP by 5-MF and 2'-MF might provide a mechanism by which TRAIL-resistant leukemia MOLT-4 cells were sensitized to these MF-derivatives." (PMID 22185222, 2011). "Through down-regulation of myeloid-cell leukemia 1 (MCL1) and induced expression of the pro-death proteins NOXA and PUMA, azacitidine may synergistically inhibit the pro-survival proteins MCL1 and BCL-XL, thereby increasing the dependence of leukemia cells on BCL2." (PMID 37190327, 2023). "In addition, studies also found that a low dose (300 nM) of MG-132 combined with flavopiridol could induce apoptosis of leukemia cells by reducing the amounts of XIAP and Mcl-1 and the activity of NF-κB63." (PMID 37537243, 2023). "Through downregulation of myeloid-cell leukemia 1 (MCL1) and induced expression of the pro-death proteins NOXA and PUMA, azacitidine or cytarabine synergistically inhibits the pro-survival proteins MCL1 and BCL-XL, thereby increasing the dependence of leukemia cells on BCL2." (PMID 37627199, 2023). "MCL-1 inhibitors resensitizes AML to BCL-2 inhibition by regulating leukemia cell bioenergetics and carbohydrate metabolism, including the TCA cycle, glycolysis and pentose phosphate pathway and modulating cell adhesion proteins and leukemia-stromal interactions." (PMID 36544784, 2022). "Downregulation of MCL-1 via inhibition of translation, but not decreased protein stability or increased ubiquitination, was reported to be the main mechanism of apoptosis in human leukemia cells." (PMID 33199836, 2021). "Within 13 days, the recipient mice treated with vehicle control rapidly succumbed to leukemia irrespective of whether they were transplanted with p185+ B-ALL cells re-programmed with human BCL-2 or human MCL-1." (PMID 26862853, 2016). "Previous studies have documented synergistic anti-leukemia efficacy of dual BCL-2/XL inhibitor ABT-737 in ALL cells, including xenograft models upon combination with VXL, the regimen used here; this synergy was attributed to the ability of L-ASP to downregulate MCL-1 protein levels." (PMID 26711339, 2015). "Relative to other hematological malignancies, CLL is a non-proliferative form of leukemia associated with constitutive activation of the B-cell receptor signaling pathway and overexpression of the B-cell lymphoma 2 (BCL-2) family of anti-apoptotic proteins (e.g., BCL-2, MCL-1)." (PMID 34041038, 2021).
leukemia (continued). "Both MIM1- and UMI-77-induced NOXA through the unfolded protein response pathway, and sensitized leukemia cells to ABT-199; this cytotoxicity was dependent on NOXA suggesting that these compounds do not directly target MCL1." (PMID 30796196, 2019). "At the same time RNAPII CTD S2 and MCL1, which are strongly dependent on the activity of CDK9 in leukemia cells, were not affected." (PMID 28422713, 2017). "A silencing approach was used for determining BAG1's role in AML, finding that its down-regulation decreased expression of BCL2, BCL-XL, MCL1, and phospho-ERK1/2, all proteins able to sustain leukemia, without affecting the pro-apoptotic protein BAX." (PMID 22016818, 2011).
lung carcinoma (171 papers, 2006 to 2026). "The Bcl-2 family, including Bcl-2, Bcl-xL, and Mcl-1, consists of key antiapoptotic proteins linked to lung cancer progression." (PMID 40732250, 2025). "In EGFR-mutated and ALK-rearranged lung cancer cell lines, MCL1 translocates to the nucleus and binds to FBW7 after TKI treatment, which leads to the degradation of MCL1." (PMID 39122703, 2024). "It is also reported that inhibition of both BCL-XL and MCL1 in cell culture models promotes extensive apoptosis in EGFR-mutated lung cancer cells that display an EMT phenotype." (PMID 39122703, 2024). "This competition between MALAT1 and MCL1 causes a decrease in MCL1 expression and a consequent increase in drug resistance in lung cancer." (PMID 34489556, 2022). "An analysis of cancer specimens revealed that up to 50% of lung cancer specimens exhibited elevated levels of Mcl-1 expression, which is associated with a poor prognosis for lung cancer patients." (PMID 32260280, 2020). "Consistently, the protein analysis of Mcl-1, Bcl-2, and Bax indicated that treatment of the cells with TM-(–)-18 and TM-(–)-4a caused a dramatic reduction in the Mcl-1 protein in all the primary lung cancer cells." (PMID 32260280, 2020). "Increase in levels of Mcl-1 has been associated with advanced staging in breast, colon and lung cancers, but its status in pancreatic tumors remained poorly understood." (PMID 24025188, 2013). "A previous study also revealed that high expression of Mcl-1 in 3D lung cancer spheroids caused its drug resistance." (PMID 21305058, 2011). "We reported previously that mtDNA mutations that induce complex I defects in mouse lung carcinoma cells can increase the metastatic potential via ROS overproduction and resultant overexpression of Hif1α and Mcl-1." (PMID 21853128, 2011). "Additionally, our study suggests LKB1 loss as a genotypic marker for sensitivity to KRASG12C-selective inhibitors + MCL-1 inhibitors in LKB1-deficient KRAS-mutant lung cancer cells." (PMID 40316540, 2025). "Similarly, other research has demonstrated that hnRNP I can facilitate the association of AGO2 with MCL1 mRNA via the miR-101-loaded miRISC, thus inhibiting the expression of MCL1 and suppressing its antiapoptotic and prosurvival effects on lung cancer cells." (PMID 38689093, 2024). "Recent studies suggest that anti-apoptotic molecules such as BCL-XL and MCL1 may function in DTP formation in EGFR-mutated lung cancer." (PMID 39122703, 2024). "Although genetically elevated Mcl1 levels have been reported in many tumor types, it has been implicated in therapeutic resistance of breast and lung cancers, with some studies showing that Mcl1 expression can mediate resistance to Navitoclax or Venetoclax, Gemcitabine, Vincristine and Taxols." (PMID 34753495, 2021). "Understanding the mechanism of how arsenic and BaP co-exposure up-regulates MCL-1 protein levels may identify additional targets to prevent and treat arsenic and BaP co-exposure-caused lung cancer." (PMID 32802178, 2020). "High expression of Mcl-1 in 3D lung cancer spheroids caused its drug resistance." (PMID 22737246, 2012). "For instance, USP13 deubiquitinated c-MYC in glioblastoma and lung squamous cell carcinoma to promote disease progression; USP13 oncogenically stabilized MCL-1 in ovarian and lung cancer and de-sensitized tumor cells to BH3 mimetic inhibitors." (PMID 41315297, 2025). "The positive correlation between MCL1 and ARD1 mRNA levels in colon and lung cancer tissues further supports the notion that ARD1 inhibits apoptosis by regulating MCL1 transcription." (PMID 40026288, 2025). "MCL-1 overexpression in humans is correlated to poor prognosis in numerous cancers, such as gastric cancer, lung cancer, and hematological malignancies." (PMID 40380182, 2025).
lung carcinoma (continued). "The gain of IGF1R in PRKCSH-deficient cells increased caspase-8 phosphorylation and Mcl-1 expression levels, whereas IGF1R knockdown reduced caspase-8 phosphorylation and Mcl-1 expression levels in lung cancer cells." (PMID 38200153, 2024). "The overexpression of Mcl-1L in PRKCSH-deficient cells suppressed TRAIL-mediated cell death and caspase-9 activation, whereas Mcl-1 depletion in lung cancer cells enhanced TRAIL-mediated cell death and caspase-9 activation." (PMID 38200153, 2024). "Co-treatment of Mcl-1-sensitive and Mcl-1insensitive lung cancer derived xenografts with 26 anddocetaxel or topotecan, respectively, resulted in an enhanced tumorresponse." (PMID 39102508, 2024). "RT exhibited apoptotic effects in lung cancer cells by specifically targeting the anti-apoptotic protein Mcl-1 and promoting the degradation of Mcl-1 through proteasomes." (PMID 38132948, 2023). "A similar role for MCL1 has been found in lung cancer, where MCL1 also activates the Akt signaling, as well as in colorectal cancer, where MCL1 has been associated with metastasis." (PMID 38139010, 2023). "Published results suggest that the high expression of a pro-apoptotic Bax protein was associated with poor prognosis in esophageal, squamous cell carcinoma, Bak in bladder cancer and Mcl-1 protein defined as unfavorable prognostic marker for lung cancer." (PMID 36766867, 2023). "In lung cancer, MCL1 has been suggested to play a key role in cancer stem cells, including invasion, chemotherapy resistance, and tumorigenesis." (PMID 38180107, 2023). "Targeting BMI1/MCL1 thus provides a new and promising therapeutic approach for the treatment of lung cancer." (PMID 35794816, 2022). "Artonin E is extracted from the bark of Artocarpus gomezianus; it enhances the anoikis of lung cancer cells in a dose-dependent manner by downregulating MCL-1." (PMID 36230714, 2022). "Mcl-1 is an anti-apoptotic protein that has gained increasing interest in lung cancer cell biology because it is highly expressed in lung cancer." (PMID 35447911, 2022). "Knockdown of Mcl-1 expression by miRNA-101 inhibits cell survival and proliferation and increases the sensitivity of human A549 lung cancer cells to etoposide." (PMID 35457012, 2022). "Previous studies reported that blockade of MEK1/2–ERK1/2 led to the downregulation of Mcl-1 in lung cancer cells." (PMID 35609325, 2022). "α-l-Rhamnose monosaccharide derivative (D6-MA), a novel synthetic derivative of digitoxin, has anticancer activity in lung cancer cell lines; it attenuated MCL-1 expression via glycogen synthase kinase-3β-mediated ubiquitin proteasomal degradation." (PMID 36230714, 2022). "FBXO4 is recently identified as an E3 ubiquitin ligase to interact and promote Mcl-1 ubiquitination and degradation in lung cancer." (PMID 35301297, 2022). "As the previous study revealed that TDB modulates Bcl-2 family proteins in human lung cancer cells via mediating Akt signaling, the alteration of antiapoptosis Mcl-1 and Bcl-2 proteins was additionally examined in CSC-enriched spheroids treated with TDB." (PMID 34349823, 2021). "Granzyme B was considered a hydrolase enzyme leading to tumor cell apoptosis but IFNγ induced STAT3-mediated PD-L1 and MCL1 expression in EGFR-positive lung cancer cells." (PMID 34685495, 2021). "It has been reported that saponin-related compounds induce lung cancer cell apoptosis by increasing the ratio of proapoptotic Bax/antiapoptotic Bcl-2 and decreasing antiapoptotic Mcl-1." (PMID 33750378, 2021). "Here, we demonstrated that Mcl-1 levels appeared to increase in paclitaxel-resistant lung cancer cells and in the tumor nodules of mice who completed the paclitaxel treatment cycles." (PMID 33824297, 2021). "This study, therefore, provides intriguing evidence that microtubule PTMs confer paclitaxel resistance by altering acetylation and targeting to the antiapoptotic Mcl-1 protein in lung cancer cells." (PMID 33824297, 2021).